MUC1 (mucin 1, cell surface associated)
Diseases named in the same sentence as MUC1 in open-access papers (continued):
Sharing a sentence is not in itself a finding about the gene and the disease.
cancer (continued). "Circulating MUC1 IgG abs have also been reported in patients with head and neck squamous cell carcinoma, multiple myeloma, and colorectal adenoma and cancer [55,64,67,68,], and are been evaluated as part of a panel of autoantibodies to TAA for the early diagnosis of cancer." (PMID 24212946, 2011). "Thus, an assay based solely on aberrant glycoforms of MUC1 applied to sera from individuals without clinical symptoms would not necessarily distinguish between the different carcinomas." (PMID 21385452, 2011). "Interestingly, normal human mammary cells that express the fully glycosylated MUC-1 were not affected by the conjugated MUC-1 aptamers upon PDT thus demonstrating remarkable cancer cell-targeting specificity of these aptamers." (PMID 27713328, 2010). "Increased MUC1 localisation at the cell surface could reduce intercellular adhesion and promote invasiveness, and increased MAL2 expression would thus be expected to have adverse significance in cancer cells." (PMID 19175940, 2009). "All samples were analyzed (n = 146); most malignant, benign and normal breast samples expressed MUC1; despite the stage of the disease, malignant tumors showed reactivity mainly at the cytoplasm with a non-apical pattern although frequently plasmatic membranes also showed staining (mixed pattern)." (PMID 19715603, 2009). "However, the effect of rs4072037 on this splicing event in healthy non-cancer tissues and on the additional spliceoforms of MUC1, including those lacking the polymorphic tandem repeat (TR) domain, has never been investigated." (PMID 19238635, 2008). "Additionally, a set of literature-reported cancer autoantigens was found in Meta-UP but not in Meta-DOWN, including Mucin 1 (MUC1), the tumor associated calcium signal transducer 1 (TACSTD1), and the heat-shock protein 90 (HSPCA)." (PMID 18173842, 2008). "The ability of both ligands to simultaneously engage the MUC1 tandem-repeat domain without inducing unfavorable steric or energetic penalties supports the rational design of multi-ligand nanocarrier systems for improved delivery and specificity in MUC1-overexpressing cancers." (PMID 41471303, 2025). "In addition, our MUC1-Vax-DC vaccine has some potential clinical applications and challenges; therefore, it is of great significance to test whether this novel human MUC1-Vax-DC vaccine can induce anti-PD-L1 antibody and CTL reaction in cancer patients, and to test the safety of this vaccine." (PMID 35891256, 2022). "In addition, the MUC1 inhibitory peptide, PMIP, that contains the β-catenin/p120-catenin binding motif present in the MUC1-CT, blocked CS-induced interaction between MUC1-CT and p120-catenin, thus stabilizing adherens junctions and decreasing cancer progression." (PMID 29186029, 2017). "Therefore, future studies are warranted to understand the roles of MUC1 in non-epithelial cells, such as alveolar type II pneumocytes and fibroblasts during airway infection, and their potential contributions to inflammation and cancer." (PMID 29186029, 2017). "Although the tumor-associated antigen MUCl could be a potential target molecule for a protective immune response against MUC1-expressing carcinoma cells, tumors are not normally rejected by the host's immune system, despite the fact that MUC1-specific CTLs have been detected in cancer patients." (PMID 19534821, 2009). "In summary, MUC1 and MUC16, key molecules within the mucin family, exhibit roles in cancer biology surpassing the conventional barrier formation in normal epithelial cells." (PMID 38361923, 2024). "subclassified AoV carcinoma based on CDX2 and MUC1 expression, finding that the PB phenotype (MUC1 positive and CDX2 negative) correlated with a poorer prognosis." (PMID 37783755, 2023). "In contrast, the triple negative (HER2‐/ER‐/PR‐) MDA MB231 cells showed negligible fluorescent signal for HER2, ER, and PR, but were positive for cancer markers (EGFR (not shown) and MUC1 and EpCAM)." (PMID 35508767, 2022).
cancer (continued). "The objective of this study is to determine the efficacy of PD-1 and PD-L1, UTLA-4, MUC1, and EGFR drugs in the treatment of smokers and non-smokers among NSCLC and other cancer patients." (PMID 34575691, 2021). "Other studies have confirmed the progressively increased staining for MUC1/DF3 from normal salivary gland to non-recurrent PA, recurrent PA, and carcinoma ex PA." (PMID 28555187, 2017). "In Case 2, the neoplastic and carcinoma cells were strongly positive for MUC5AC and MUC6 but only focally positive or negative for MUC1, MUC2, CDX2, CK7, and CK20, suggesting that this immunophenotype was compatible with the gastric type." (PMID 27656307, 2016). "In Case 1, the dysplastic and carcinoma cells were strongly positive for CK7, MUC1, and MUC6 but negative or only focally positive for CK20, MUC2, CDX2, and MUC5AC." (PMID 27656307, 2016). "NAF anti-MUC1 IgA levels in cancers with LVI and in Her2-neu positive cancers were significantly higher than those without these features (P = 0.005, P = 0.02, resp)." (PMID 26693201, 2015). "In the present study, we examined the expression patterns of MUC1 and MUC4 in non-neoplastic bladder urothelium and malignant neoplasms of bladder tissues on tissue microarrays (TMA) and tissue sections from the urinary bladder biopsies and resected samples." (PMID 24671186, 2014). "Although WT1, MUC1, and CA125 are considered tumor antigens and potential targets for cancer immunotherapy, no reports are available on these antigens in ROC." (PMID 25298213, 2014). "Most slides from cancer-free tissue lacked expression of CCND1, CD44, CDH1, EGFR, ERBB2, KIT, keratins, NOTCH1, PAK1, PTGS2, SNAI1, and VIM but showed staining of MUC1, HIF1A, NKX2-1, SFTPC, and STAT3, which were also found in AdCa." (PMID 23028920, 2012). "Neither cytoplasmic nor membranous MUC1 in primary tumors had prognostic impact, whether analyzed in the entire cohort or in stages I–II versus III–IV, and whether assessed in all carcinoma cells, MIPs, cribriform, or solid structures." (PMID 41332218, 2025). "Moreover, exposure of the HLA-A2/A24− AsPC-1 carcinoma cell line to 10 Gy of 223Ra over 96 hours did not result in any significant lysis by any of the CEA, MUC-1, or brachyury CTLs used in this study." (PMID 27893426, 2016). "In this study, we investigated the relationships between mucin expression and clinicopathologic factors in 60 SBC cases, in which expression profiles of MUC1, MUC2, MUC3, MUC4, MUC5AC, MUC6 and MUC16 in cancer and normal tissues were examined by immunohistochemistry." (PMID 24722639, 2014). "Furthermore, general up-regulation of MUC1 and MUC16, independent of specific glycan expression, protects Capan-1 cancer cells from ADCC and CTL-mediated killing." (PMID 24039759, 2013). "Unlike the less consistent expression patterns of MUC1, MUC6 and MUC5AC in normal and cancer tissues, MUC2 levels were always measured low in normal endometrial and cervical tissue, and elevated MUC2 expressions were specifically found in various neoplastic lesions." (PMID 22417007, 2012). "In a multivariate model, MUC1 (odds ratio, OR = 28.95, 3+ vs. negative expression, p = 0.004) and MSLN (OR = 12.47, 3+ vs. negative expression, p = 0.01) were highly predictive of early cancer-specific death." (PMID 22792233, 2012).
adenocarcinoma (131 papers, 2003 to 2026). A common cancer characterized by the presence of malignant glandular cells. "MUC1 tumor-associated antigen is a current target of immune therapy in numerous adenocarcinoma types, including EOC." (PMID 40642792, 2025). "Incorporating MUC1 – a glycoprotein whose aberrant glycosylation drives adenocarcinoma progression – broadens the panel’s diagnostic utility." (PMID 41142941, 2025). "Mucin 1 (MUC1) is a membrane-associated macromolecule glycoprotein that is overexpressed in most adenocarcinomas." (PMID 36839042, 2023). "Overexpression of MUC1 is found in approximately 95% of human adenocarcinomas, where it is associated with oncogenic activity." (PMID 22073229, 2011). "Within the last three decades, MUC1 has been recognized as the candidate anticancer therapeutic target due to its upregulated expression, abnormal glycosylation, and polarization loss within numerous adenocarcinomas." (PMID 35883508, 2022). "However, aberrantly glycosylated, overexpressed MUC1 is a distinguishing feature of a large number of adenocarcinomas associated with lung, breast, pancreatic, ovarian, prostate, and colon cancers." (PMID 31468283, 2019). "MUC1 protein is an important tumor-associated antigen (TAA) detected in most adenocarcinomas." (PMID 21912664, 2011). "MUC1 is a tumor-associated transmembrane antigen expressed at low levels on the apical surface of ductal epithelial cells in several organs, and overexpressed in the majority of adenocarcinomas and their precursor lesion, where its tandem repeat region is reported to have truncated O-glycans." (PMID 36980805, 2023). "The vaccines target Carcinoembryonic Antigen (CEA) and Mucin 1 (MUC-1), proteins commonly overexpressed in adenocarcinomas, and were combined with sargramostim (GM-CSF) to enhance immune response without significant toxicity." (PMID 40762664, 2025). "Epithelial MUC1 is a high‐molecular‐weight membrane glycoprotein that is frequently overexpressed and aberrantly glycosylated in adenocarcinoma." (PMID 40033767, 2025). "In the clinical setting, immunohistochemistry was not employed to select WT1 and MUC1 peptides because previous studies reported the overexpression of WT1 and MUC1 in adenocarcinoma of gastrointestinal cancers." (PMID 39737308, 2024). "MUC1 has a barrier function against bacterial invasion and is well known for its aberrant expression and glycosylation in adenocarcinomas." (PMID 38508723, 2024). "Many human clinical studies have been undertaken to demonstrate the efficacy of oxidized mannan-MUC1 fusion protein (M-FP) as an anticancer vaccine in MUC1+ adenocarcinoma patients." (PMID 37242947, 2023). "A total of four studies looked specifically at the adenocarcinoma of the oesophago-gastric junction (GOJc), analysing MUC1, MUC2, MUC5AC and MUC6 in 191 surgically resected specimens." (PMID 37958425, 2023). "MUC-1, a kind of human epithelial mucin, shows extensive expression within adenocarcinomas (80% of BRCAs are included), whereas erbB-2 overexpression is detected in around 30% of BRCAs." (PMID 35883508, 2022). "In contrast to normal apical localization of MUC1, a basolateral expression is present in solid high-grade adenocarcinoma." (PMID 35205621, 2022). "Apart from that, a Phase I trial adopted AR20.5 to induce MUC1-specific immunity for treating advanced adenocarcinoma cases." (PMID 35883508, 2022). "In this work, a first-in-human study of this combination vaccine construct, we undertake a Phase 1 trial in a cohort of 21 patients with MUC1-overexpressing adenocarcinomas." (PMID 36307410, 2022). "We report a phase 1 study of Ad-sig-hMUC1/ecdCD40L (NCT02140996), an adenoviral-vector vaccine encoding the tumour-associated antigen MUC1 linked to CD40 ligand, in patients with advanced adenocarcinoma." (PMID 36307410, 2022).
adenocarcinoma (continued). "The loss of the well-organized structure of the gland rendering it without demarcation of the apical and basolateral epithelial cells yet with ultimate expression of MUC1 is characteristic of adenocarcinoma." (PMID 33670011, 2021). "CK7, MUC1 and EpCAM were chosen as representative markers because they are frequently expressed in adenocarcinoma." (PMID 34600546, 2021). "Since systemic targeting of MUC1 in several adenocarcinomas is being actively explored, the fact that MUC1 is involved in a regulatory mechanism of expansion and immunosuppressive activity of MDSCs is of high significance." (PMID 34070449, 2021). "This is in line with the long-held assertion that MUC1 is widely expressed in all forms of adenocarcinoma." (PMID 32377198, 2020). "A glimpse of this challenge is illustrated using the example of a ubiquitous adenocarcinoma tumor antigen MUC1 mucin as follows." (PMID 31468283, 2019). "The aberrant MUC1 is overexpressed in almost all human adenocarcinomas, including lung, colon, pancreatic, breast, ovarian, and prostate cancers." (PMID 30699986, 2019). "Aberrant expression of glycoform has been found on the cell membrane mucin-1 (MUC1), a large protein carrying O-glycan over-expressed by most adenocarcinomas." (PMID 29568411, 2018). "MUC1 mucin (CD227) has long been known to be expressed by epithelial cells and overexpressed by a multitude of adenocarcinomas." (PMID 30405607, 2018). "Several clinical trials have been done and are currently ongoing examining the potential of various formulations of MUC1-derived products, as new candidates for immunotherapy of several adenocarcinomas." (PMID 30405607, 2018). "Mucin 1 (MUC1) is a cell surface glycoprotein that is overexpressed and aberrantly glycosylated on the cell surface of a majority of human adenocarcinomas." (PMID 30149585, 2018). "In normal epithelia, VNTR is highly glycosylated in Serine and Threonine whereas in most adenocarcinomas such as those of breast, ovary, colon, pancreas, lung, and in premalignant lesions MUC1 becomes over-expressed and hypoglycosylated." (PMID 28483926, 2017). "The abnormal hypoglycosylated form of the epithelial mucin MUC1 is over-expressed in chronic inflammation and on human adenocarcinomas, suggesting its potential role in inflammation-driven tumorigenesis." (PMID 29285251, 2017). "Lamin A and EMA (epithelial membrane antigen, also known as MUC-1) protein expression was then specifically studied in these adenocarcinoma cells." (PMID 28806747, 2017). "We observed strong HMPV staining on all adenocarcinoma tissues consistent with overexpression of MUC1, as well as expected weaker staining on the apical surface of the epithelial cells lining the ducts of normal tissues." (PMID 27545199, 2016). "Specimens of adenocarcinoma samples revealed strong staining with both MUC1 VU4H5 and anti-CIN85 antibodies." (PMID 25675408, 2015). "Mucin1 (MUC1), as an oncogene, plays a key role in the progression and tumorigenesis of many human adenocarcinomas." (PMID 26057631, 2015). "In patients, MUC1 overexpression on developing adenocarcinomas leads to spontaneous humoral responses to various MUC1 epitopes from its extracellular domain." (PMID 25078979, 2014). "Univariate analysis showed that adenocarcinoma histology, EGFR mutations, and blood MUC1 and VEGF mRNA positivity were associated with PFS." (PMID 25410981, 2014). "In most adenocarcinomas and in other inflammatory diseases of epithelial tissues, MUC1 is overexpressed and loses the polarity of its expression." (PMID 24072600, 2013). "MUC1 is considered a valuable target for ligand-guided anticancer chemotherapy due to its over-expression in most adenocarcinomas." (PMID 22384115, 2012). "Loss of polarization, overexpression and aberrant glycosylation of MUC1 in mucosal inflammation and in adenocarcinomas induces humoral immune responses to the mucin." (PMID 24212946, 2011).
adenocarcinoma (continued). "MUC1 mucin is a large transmembrane glycoprotein, whose expression increased at least 10-fold in most malignant adenocarcinomas, making it an ideal target molecule for chemotherapeutics." (PMID 21912664, 2011). "MUC1 protein is an attractive target for anticancer drug delivery owing to its overexpression in most adenocarcinomas." (PMID 21912664, 2011). "Another study evaluated the influence of cyclophosphamide and the route of injection on mannan-MUC1 peptide immunization in 41 patients with metastatic or locally advanced adenocarcinomas, mainly of the breast, colon and rectum." (PMID 24212946, 2011). "Several clinical trials have been carried out with a MUC1 fusion protein coupled to mannan or to oxidized mannan in patients with adenocarcinoma." (PMID 24212946, 2011). "Mucin 1 (MUC1) is a high molecular weight glycoprotein overexpressed on adenocarcinoma cells and is a target for immunotherapy protocols." (PMID 16776849, 2006). "MUC1 expression was found in most adenocarcinomas of the breast, lung, stomach, pancreas, prostate and ovary, and a diffuse cytoplasm MUC1 immunostaining was associated with a high Gleason score." (PMID 14760390, 2004). "Accordingly, enhancement of endogenous immune responses to MUC1 by active specific immunisation based on designed MUC1 vaccines is predicted to improve long-term survival of patients with MUC1+ adenocarcinomas." (PMID 12966437, 2003). "For example, a mixture of genistein and retinoic acid (ATRA) significantly inhibits the invasion ability of human adenocarcinoma cells (A549 cell line) by downregulating the transmembrane protein mucin 1 (MUC1) as well as intercellular adhesion molecules-1 (ICAM1) expression." (PMID 39940882, 2025). "However, MUC1 is most well known for its aberrant expression and glycosylation in different types of adenocarcinomas." (PMID 38508723, 2024). "Importantly, we also identified the oral taxa Porphyromonas and Megasphaera to be enriched in adenocarcinoma with low MUC1 and MUC5AC expression, respectively." (PMID 37085819, 2023). "In normal epithelia, VNTR is highly glycosylated in Serine and Threonine, whereas in most adenocarcinomas such as those of breast, ovary, colon, pancreas, lung, head, and neck, as well as in premalignant lesions, MUC1 becomes over-expressed and hypoglycosylated." (PMID 37896984, 2023). "Cigarette smoke in vitro increases MUC1 in adenocarcinoma cells." (PMID 35205621, 2022). "In addition, MUC1, which is a cell wall-based mucin glycoprotein present on the apical surface of epithelial cells, is highly expressed in many adenocarcinomas." (PMID 32754277, 2020). "Similarly, in the spontaneous model of PDA that expresses human MUC1, the combination treatment stalled the progression of pancreatic intraepithelial pre-neoplastic (PanIN) lesion to adenocarcinoma." (PMID 31114758, 2019). "Specifically, multivalent bispecific aptamers targeting MUC1 and lymphocytes may serve as a new strategy for treatment of most adenocarcinomas." (PMID 30699986, 2019). "MUC1 has been considered a possible therapeutic target for the past 30 years as it is up-regulated, aberrantly glycosylated and its polarization is lost in many adenocarcinomas." (PMID 29784646, 2018). "First of all, the most common pathological classification of CRC was adenocarcinoma with various differentiation degrees in the included studies, the correlation of MUC1 expression with other pathological types or certain differentiation degree was not evaluated sufficiently." (PMID 26367866, 2015). "MUC1 is a transmembrane glycoprotein abnormally expressed in human adenocarcinomas." (PMID 24072600, 2013). "Since MUC1 is over-expressed in most adenocarcinomas, the aptamer may have potential utility as a guiding ligand for targeted chemotherapy against these malignancies." (PMID 22384115, 2012). "Among the 197 adenocarcinoma lesions, MUC1/DF3 was expressed in 62 lesions (31%)." (PMID 23152882, 2012).